HDAC3 (histone deacetylase 3)
Diseases named in the same sentence as HDAC3 in open-access papers (continued):
Sharing a sentence is not in itself a finding about the gene and the disease.
colorectal cancer (continued). "Hence, targeting USP38 as well as HDAC3 are promising strategy in overcoming chemoresistance of colorectal cancer." (PMID 32404892, 2020). "Furthermore, HDAC3 is overexpressed in a variety of cancers, including colorectal cancer, and therefore it is regarded as a promising target for cancer." (PMID 32934224, 2020). "Myc has been implicated in the transcriptional repression of miR-15a/16-1 expression in B-Cell Lymphoma, Ewing’s sarcoma and colorectal carcinoma, and was also shown to interact with HDAC3 to indirectly repress expression of miR-15a/16-1 in Mantle Cell Lymphoma (MCL)." (PMID 31289611, 2019). "Overexpression of HDAC3 in colorectal cancer cells is known to decrease expression of p21." (PMID 30583572, 2018). "However, the mechanism by which HDAC3 was recruited to specific promoters that plays critical roles in colorectal cancer is largely unknown." (PMID 32404892, 2020). "The positive regulatory effect of USP38 on HMX3 expression indicates that in colorectal cancer, USP38 can influence tumor cell growth by regulating multiple signaling pathways (such as the USP38/HDAC3 signaling axis and the USP38/LSD1 signaling axis)." (PMID 40936898, 2025). "​In colorectal carcinoma, CBX4 suppresses metastasis by recruiting histone deacetylase 3 (HDAC3) to the runt-related transcription factor 2 (Runx2) promoter, leading to transcriptional repression of Runx2, a key factor in cancer metastasis." (PMID 40740235, 2025). "In colorectal cancer, CBX4 suppresses metastasis by recruiting HDAC3 to deacetylate histone H3K27 at the RUNX2 promoter, consequently inhibiting RUNX2 expression." (PMID 38816356, 2024). "Conversely, in colorectal carcinoma, CBX4 suppresses RUNX2 expression by recruiting HDAC3 to the Runx2 promoter." (PMID 38816356, 2024). "We also demonstrated that MPT0G236 inhibited the activity of Class I HDACs (HDAC1, HDAC2, HDAC3, and HDAC8), as well as of a Class IIb HDAC, HDAC6, leading to the increased acetylation of α-tubulin and histone H3 in both colorectal cancer cells." (PMID 37628767, 2023). "In colorectal cancer, CBX4 can interact with histone deacetylase 3 (HDAC3) to maintain recruited HDAC3 to the Runx2 promoter, which maintains a deacetylated histone H3K27 state to inhibit Runx2 expression, consequently repressing tumor metastasis." (PMID 33464142, 2021). "LncRNA-LET inhibits the metastasis of HCC and colorectal cancer cells, which are suppressed by HDAC3 (histone deacetylase 3) in hypoxia conditions." (PMID 29416704, 2018). "HDAC3 directly regulates the expression of EGFR by binding to promoter sequences of EGFR, while HDAC inhibitors can reverse the expression of EGFR in colorectal cancer cells." (PMID 30583572, 2018). "Class-I HDACs consisting of HDAC1, HDAC2, HDAC3 and HDAC8, are well known oncogenic proteins expressed at high levels in malignant cervical and colorectal cancers." (PMID 29190639, 2017). "In colorectal cancer, overexpression of USP38 can activate downstream tumor-suppressive signaling pathways by promoting the expression of key regulatory factors such as HMX3 and HDAC3." (PMID 40936898, 2025). "Therefore, our work identifies an epigenetically regulated pathway, HDAC3/C/EBP-α/B7x, which is responsible for HDAC inhibitor resistance in colorectal cancer, and also provides a promising therapeutic approach to reverse HDAC inhibitor resistance." (PMID 32934224, 2020). "To further explore the relationship between HDAC3 and B7x, we investigated the expression level of HDAC3 in colorectal cancer cell lines, and found that there was a negative relationship between HDAC3 protein expression and B7x mRNA expression (R = −0.76)." (PMID 32934224, 2020). "Interestingly, treatment with a specific inhibitor or siRNA of HDAC3, but not HDAC2, 6, and 8, resulted in obvious upregulation of B7x expression in colorectal cancer cells." (PMID 32934224, 2020).
colorectal cancer (continued). "Although this mechanism has not been directly validated in colorectal cancer (CRC), our findings suggest that HDAC3 may similarly regulate NRF2 expression at the epigenetic level in CRC cells, thereby modulating downstream targets such as GPX4 and contributing to ferroptosis resistance." (PMID 40947430, 2025).
lymphoma (29 papers, 2014 to 2025). A malignant (clonal) proliferation of B- lymphocytes or T- lymphocytes which involves the lymph nodes, bone marrow and/or extranodal sites. "Despite selective HDAC3 inhibition showing promise in a subset of lymphomas with CREBBP mutations, wild-type tumors generally exhibit resistance." (PMID 39117798, 2024). "Based on this rationale, HDAC3 loss-of-function or selective HDAC3 inhibition has been recently shown to induce strong anti-lymphoma effects by increasing H3K27ac in CREBBP-mutant lymphoma while those effects are modest in CREBBP wild-type tumors." (PMID 39117798, 2024). "TET2 and CREBBP mutations are, in the majority of cases, mutually exclusive, so TET2 loss-of-function generates lymphoma cells that show a dependence on HDAC3." (PMID 39518937, 2024). "HDAC3 inhibition represents a novel mechanism-based immune epigenetic therapy for lymphomas caused by CREBBP mutation." (PMID 34248926, 2021). "The loss of CREBBP promotes the development of HDAC3-dependent lymphoma." (PMID 34211501, 2021). "Hence, lymphomas with CREBBP mutation become extremely dependent on HDAC3." (PMID 35237302, 2022). "This works in good correspondence with the bioinformatics analysis suggesting the significant role of HDAC3 in the survival of leukemia/lymphoma cells." (PMID 40284412, 2025). "Comparing the mechanisms by which belinostat and its hydrazide analogs exert anti-cancer effects allows for an assessment of the individual roles of HDAC1 and HDAC3 in the survival of specific leukemia and lymphoma cell types." (PMID 40284412, 2025). "Collectively, our findings establish an unprecedented link between HDAC3 inhibition and viral mimicry in lymphoma." (PMID 39117798, 2024). "Our following validation using alternative HDAC3-specific targeting compounds, a pan-HDACi, and multiple sgRNAs as well as both human and mouse lymphoma cell lines further confirmed the on-target effects and general applicability." (PMID 39117798, 2024). "Another study observed reduced Eμ‐Myc lymphoma proliferation and differentiation in acute promyelocytic leukemia using the HDAC3 inhibitor RGFP96 (APL)." (PMID 39428967, 2024). "Taken together, we identified and validated GNAS KO as a sensitizer to HDAC3 inhibition based on results of distinct sgRNAs and multiple HDAC3-targeting compounds in both human and mouse lymphoma cell lines, showing a consistent and conserved phenotype." (PMID 39117798, 2024). "In this study, we report GNAS KO as a molecular sensitizer to HDAC3 inhibition in resistant lymphoma cells." (PMID 39117798, 2024). "Here, using unbiased genome-wide CRISPR screening, we identify GNAS knockout (KO) as a sensitizer of resistant lymphoma cells to HDAC3 inhibition." (PMID 39117798, 2024). "We suggest low GNAS expression as a potential biomarker that reflects viral mimicry priming for enhanced response to HDAC3 inhibition in the clinical treatment of lymphoma, especially the CREBBP wild-type cases." (PMID 39117798, 2024). "In this study, we identify that knockout (KO) of GNAS, a gene encoding the G-protein α subunit (Gαs), sensitizes resistant lymphoma cells to HDAC3 inhibition using unbiased genome-wide CRISPR screening." (PMID 39117798, 2024). "The consequence of inactivating somatic mutations of CREBBP is promoting the role of HDAC3, which encourages the development of HDAC-3-dependent lymphomas." (PMID 39518937, 2024). "In these experiments, Hdac3 deficiency rescued repression of the Crebbp/BCL6-regulated transcripts and suppressed Crebbp-mutant lymphomas in vitro and in vivo." (PMID 38124747, 2023). "For example, researchers have found that the combination of a selective HDAC3 inhibitor with anti-PD-L1 immunotherapy enhanced tumor regression in a syngenic murine lymphoma model." (PMID 35145517, 2022). "Conversely, when HDAC3 activity was inhibited, histone acetylation was restored at these enhancers and lymphoma growth was suppressed both in vitro and in vivo." (PMID 34456919, 2021).
lymphoma (continued). "recently showed that HDAC3-selective inhibitors have a dual effect by reversing CREBBP-mutant aberrant epigenetic programming limiting lymphoma growth inhibition while restoring antitumor immunity, notably antigen presenting-genes." (PMID 34335584, 2021). "Subsequently, after interfering with HDAC3, its expression was distinctly decreased in the lymphoma cells Namalwa and Raji cells (P < 0.01)." (PMID 34658308, 2021). "First, we used qRT-PCR to detect the expression of HDAC3 in Burkitt lymphoma cell lines OCI-LY1, Namalwa, Raji, and Daudi and found that the expression of HDAC3 in lymphoma cells was notably upregulated (P < 0.01), with the highest expression in Namalwa cells." (PMID 34658308, 2021). "Protein kinase Cβ (PRKCB) plays a role in autophagy regulation, CREBBP inactivation promotes the development of HDAC3-dependent lymphomas, and abnormal expression of Casein kinase 2α1 (CSNK2A1) is linked to neurological diseases and cancer." (PMID 34211501, 2021). "We found that the expression of TCF3 and HDAC3 was up-regulated in BL tumor tissues and lymphoma cells, and the miR-101 expression was down-regulated." (PMID 34658308, 2021). "HDACs are typically recruited by oncogenic protein complexes in lymphoma and leukemia and HDAC3 inhibitors are synergistic or additive with anticancer agents for therapeutics." (PMID 24618901, 2014). "Ultimately, our findings could facilitate the clinical development of predictive and/or response biomarkers for the rational use of HDAC3-targeting agents in lymphoma, especially the CREBBP wild-type cases." (PMID 39117798, 2024). "Given that HDAC3 inhibition has been shown to exert anti-lymphoma effects through increasing H3K27ac and promoting apoptosis, we sought to examine whether GNAS KO-induced sensitization is associated with those biological events." (PMID 39117798, 2024). "Overall, our findings unveil a previously unreported viral mimicry-related mechanism and could facilitate future clinical development of predictive and/or response biomarkers in the context of HDAC3 inhibition and lymphoma treatment." (PMID 39117798, 2024). "In lymphoma and liver cancer samples, elevated B7H6 mRNA levels were linked with HDAC3 expression." (PMID 39768254, 2024). "Our TE transcriptome analysis and immunofluorescence results indicate that GNAS KO may play a role in priming resistant lymphoma to viral mimicry induction upon HDAC3 inhibition." (PMID 39117798, 2024). "Similarly, inhibition of HDAC3 in lymphoma cells resulted in nuclear export of STAT3 to the cytoplasm, thus hindering STAT3 function as a transcriptional factor." (PMID 36341403, 2022). "Particularly, c-Myc suppressed miR-29s transcription through a co-repressor complex with histone deacetylase 3 (HDAC3) and Enhancer of zeste homolog 2 (EZH2); and combined inhibition of HDAC3 and EZH2 restored miR-29s expression levels, which, in turn, caused lymphoma growth suppression." (PMID 36140219, 2022). "We propose that lack of intrafollicular CD4 + T cells can be considered as a surrogate biomarker of immune escape in a manner analogous to the case of CREBBP mutant lymphomas, which indeed benefit from HDAC3-selective inhibitors to promote immune-related activities." (PMID 34267181, 2021). "Interestingly, CREBBP-mutant lymphomas become dependent to HDAC3, the histone deacetylase opposing the effect of CREBBP, that has been identified as a relevant therapeutic target in these tumors." (PMID 34335584, 2021). "HDAC3 acts as a repressor of the PD-L1 and HDAC3 inhibitor, resulting in lymphoma regression." (PMID 31597362, 2019). "Previously, EZH2 was reported to interact with HDAC3 to repress miR-29 in lymphomas." (PMID 25644061, 2015). "Moreover, MYC was recently shown to interact with EZH2 and HDAC3 to repress miR-29 in lymphomas." (PMID 25644061, 2015). "Deacetylation of STAT3 by the histone deacetylase HDAC3 promotes STAT3 activation in hepatocytes and lymphoma cells." (PMID 36341403, 2022).
lymphoma (continued). "HDAC3 inhibition offers the potential to block the BCL6-HDAC3 complex and restore the key pathways in cell cycle and differentiation inhibited by BCL6 in CREBBP-mutant lymphomas, including Ag presentation as well as BCR, NF-kB, and interferon signaling." (PMID 35071240, 2021). "Zhang and colleagues observed the epigenetic regulation of miR-29 by targeting HDAC3, MYC, and EZH2 in lymphomas." (PMID 32411322, 2020). "To test this possibility, we determined the protein levels of HDAC3, MEF2C and c-Myc in leukemia and lymphoma cell lines." (PMID 25675295, 2015). "Furthermore, selective HDAC3 inhibitors restored immune surveillance by reactivating BCL6-repressed INF pathway and antigen presentation genes in lymphoma cells, enabling T-cells to recognize and kill them, especially in the presence of CREBBP mutation." (PMID 35237302, 2022). "HDAC3 and KDM5 inhibitors may similarly offer the potential to affect both lymphoma cells and the TME to improve the efficacy of immunotherapy." (PMID 35071240, 2021). "In addition, we have previously shown that PRMT5 associates with an NF‐κB transcriptional repressor complex containing HDAC3, which promotes deacetylation of H3K14 lysine, and triggers gene silencing in lymphoma cells." (PMID 33462997, 2021). "Suppression of HDAC3 and EZH2 cooperatively inhibited the MYC-EZH2-miR-29 axis, leading to reexpression of miR-29, therefore downregulating miR-29-targeted genes and inhibiting lymphoma progression." (PMID 32411322, 2020). "Histone deacetylase 3 (HDAC3) is recruited by the transcription repressor BCL6 to form a deacetylation complex with SMRT and NCoR to counteract the activity of CREBBP for gene enhancer regulation, which maintains the unopposed deacetylation state in CREBBP-mutant lymphoma." (PMID 39117798, 2024). "Particularly this HDAC3 involvement is of potential therapeutic interest, as subtype-specific HDAC inhibitors are currently being developed and could potentially be used to treat CREBBP-mutant lymphomas." (PMID 38124747, 2023).
atherosclerosis (27 papers, 2013 to 2026). A disease characterized by the build-up of fatty material and calcium deposition in the arterial wall resulting in partial or complete occlusion of the arterial lumen. "While HDAC3 has been previously implicated in cytokine regulation and inflammatory signaling, such as the regulation of NF-κB in atherosclerosis and pulmonary injury, its role in pulmonary vascular cell proliferation has not been clearly defined." (PMID 41543632, 2026). "Despite promising findings, significant gaps remain, particularly in understanding the cell-specific roles of histone modifiers, such as HDAC3, in diabetes-associated atherosclerosis." (PMID 40076813, 2025). "This review discusses the role of HDAC3 and its inhibitors in vascular function, inflammation, lipid accumulation and plaque stability associated with the development of atherosclerosis." (PMID 35656103, 2022). "However, HDAC3 plays a somewhat contrasting role in atherosclerosis development, which is tightly linked with endothelial dysfunction." (PMID 38397377, 2024). "Knockdown of HDAC3 exacerbates the development of atherosclerosis and causes vessel rupture." (PMID 34338228, 2021). "Additionally, histone deacetylase 3 (HDAC3) has been reported as having a protective effect in apolipoprotein E deficient (ApoE−/−) mice as it maintains the endothelial integrity and its deficiency results in atherosclerosis." (PMID 35563540, 2022). "Genetic studies using the lysozyme 2 promoter-driven Cre-lox system to delete Hdac3 in myeloid cells revealed a significant reduction in atherosclerosis in Apoe+ mice on a high-fat diet." (PMID 40076813, 2025). "Overall, modifying the macrophage epigenome can enhance the course of atherosclerosis, and identify HDAC3 as a possible new therapeutic target for cardiovascular disease (Ref." (PMID 39320855, 2024). "Of note, HDAC3 expression was upregulated in atherosclerotic plaque in a mouse model of atherosclerosis and regulated the induction of EndMT." (PMID 39050859, 2024). "Functionally, the pharmacological inhibition of HDAC3 in a mouse model of atherosclerosis reduced atherosclerotic lesions and inhibited EndMT, whereas the genetic overexpression of HDAC3 induced EndMT in HUVECs." (PMID 39050859, 2024). "HDAC3 protects against atherosclerosis through inhibition of inflammation via the microRNA-19b/PPARγ/NF-κB axis in ox-LDL treated HUVECs and ApoE−/− mice." (PMID 38031118, 2023). "Animal experiment has confirmed that an imprinted antisense IncRNA in the KCNQ1 gene promotes macrophage lipid accumulation and accelerates the development of atherosclerosis through the miR-452-3p/HDAC3/ABCA1 pathway." (PMID 36539828, 2022). "kcnq1ot1 promotes macrophage lipid accumulation and accelerates the development of atherosclerosis via the miR-452-3p/HDAC3/ABCA1 pathway." (PMID 35806493, 2022). "In atherosclerosis, kcnq1ot1 enhances HDAC3 expression by competitively binding to miR-452-3p, thereby inhibiting ABCA1 expression as well as cholesterol efflux." (PMID 35806493, 2022). "Taken together, these findings suggest that kcnq1ot1 promotes macrophage lipid accumulation and accelerates the development of atherosclerosis through the miR-452-3p/HDAC3/ABCA1 pathway." (PMID 33293505, 2020). "On the contrary, compelling evidence indicates that endothelial cell–specific HDAC3 depletion substantially enhances IH in an atherosclerosis mouse model." (PMID 30623138, 2018). "While HDAC3 was the sole HDAC isoform upregulated in ruptured lesions of atherosclerosis, HDAC3 deletion has been shown to shift plaque macrophages to an anti-inflammatory phenotype and reduce lipid accumulation." (PMID 27904654, 2016). "Collectively, we show that targeting the macrophage epigenome can improve atherosclerosis outcome and we identify Hdac3 as a potential novel therapeutic target in cardiovascular disease." (PMID 25007801, 2014).